CIRSR (corepressor of RBPJ and splicing regulator)
Description:
May modulate splice site selection during alternative splicing of pre-mRNAs (By similarity). Regulates transcription and acts as corepressor for RBPJ. Recruits RBPJ to the Sin3-histone deacetylase complex (HDAC). Required for RBPJ-mediated repression of transcription.
Synonyms: CIR; CIR1; THE1B/CIR1
Tractability: Small molecule: a structure with a bound ligand is known. PROTAC: UniProt records ubiquitination sites on it; ubiquitination databases record sites on it; its protein half-life has been measured.
Gene: Protein-coding gene on chromosome 2 (174,348,022 to 174,395,712, reverse strand). Ensembl gene ENSG00000138433.
Subcellular location: Nucleus speckle; Cytoplasm, cytoskeleton, microtubule organizing center, centrosome
Subcellular location (Human Protein Atlas): Nuclear speckles
Gene Ontology:
Molecular function: histone deacetylase binding; protein binding; protein kinase binding; protein-containing complex binding; transcription corepressor activity
Biological process: negative regulation of DNA-templated transcription; negative regulation of transcription by RNA polymerase II; mRNA splicing, via spliceosome
Cellular component: centrosome; nuclear speck; nucleus; protein-containing complex; spliceosomal complex; U2-type catalytic step 1 spliceosome
Genetic constraint (gnomAD): Loss-of-function variants: 12 observed, 20.02 expected, observed/expected ratio (o/e) 0.6, 90% interval 0.38 to 0.97. The upper end of that interval is the gene's LOEUF score, 0.97, which puts it in group 4 of 6, group 1 being the genes least tolerant of losing a copy. Missense variants: 334 observed, 402.91 expected, observed/expected ratio (o/e) 0.83, 90% interval 0.76 to 0.91. Synonymous variants: 149 observed, 137.69 expected, observed/expected ratio (o/e) 1.08, 90% interval 0.95 to 1.24.
Homologues: Orthologues: chimpanzee CIR1 (99% identical), macaque CIR1 (93% identical), dog CIR1 (88% identical), pig CIR1 (85% identical), rabbit CIR1 (85% identical), rat Cir1 (79% identical), mouse Cir1 (78% identical), guinea pig CIR1 (69% identical), tropical clawed frog cir1 (56% identical), zebrafish cir1 (44% identical), Caenorhabditis elegans cir-1 (41% identical), Drosophila melanogaster CG6843 (36% identical).